SNAP23 (synaptosome associated protein 23)
Diseases named in the same sentence as SNAP23 in open-access papers (continued):
Sharing a sentence is not in itself a finding about the gene and the disease.
Chlamydia infection (1 paper, 2019). "In summary, our data show that the loss of both SNAP-23 and Syntaxin 4 results in an aberrant increase in LD production during Chlamydia infection." (PMID 32025513, 2019). "Rather, the role of SNAP-23 and Syntaxin 4 in the regulation of LDs is specific to Chlamydia infection." (PMID 32025513, 2019). "We then demonstrate that the loss of both of these SNARE proteins results in the dysregulation of Chlamydia-induced lipid droplets, indicating that both SNAP-23 and Syntaxin 4 play a critical role in lipid droplet homeostasis during Chlamydia infection." (PMID 32025513, 2019). "Together, these results demonstrate that both, SNAP-23 and Syntaxin 4, control LD homeostasis specifically during Chlamydia infection and that this effect can be boosted with exogenous FAs." (PMID 32025513, 2019). "To identify the specific role of SNAP-23 and Syntaxin 4 during Chlamydia infection, we assessed whether Chlamydia targets the plasma membrane SNAREs to hijack secretory cargo destined for the plasma membrane." (PMID 32025513, 2019). "To determine whether the plasma membrane SNAREs SNAP-23, Syntaxin 3, and Syntaxin 4 play a role during Chlamydia infection, we first assessed their localization during infection." (PMID 32025513, 2019). "Thus, we investigated whether SNAP-23, Syntaxin 3 or Syntaxin 4 play a role in LD dynamics during Chlamydia infection." (PMID 32025513, 2019). "Altogether, these data suggest that the role of SNAP-23 and Syntaxin 4 during Chlamydia infection is independent of their canonical roles in mediating membrane fusion at the plasma membrane." (PMID 32025513, 2019). "Since these SNAREs are recruited to the inclusion, we tested whether Chlamydia infection impacts Syntaxin 3/SNAP-23 and Syntaxin 4/SNAP-23 t-SNARE complex formation." (PMID 32025513, 2019). "In light of these observations, the role of SNAP-23 and Syntaxin 4 during Chlamydia infection is likely independent of constitutive secretion." (PMID 32025513, 2019).
cognitive decline (1 paper, 2025). "Patients involved in immunovascular signaling (MMP8), synaptic vesicle fusion (SNAP23) and lipid trafficking (APOB) pathways relevant to APOE biology and cognitive decline." (PMID 40665048, 2025).
depression (1 paper, 2024). "As an important factor both on glutamate release and on IGF-1 localization in CNS, SNAP23 is evidenced to be closely related to depression." (PMID 38674428, 2024). "Accordingly, SNARE interactions in the vesicular transport pathway that involve SNAP23 and VTI1A is proven to be a vital signaling pathway in the patients with PCOS and depression." (PMID 38674428, 2024). "There were five overlapping hub genes in the two datasets including CASP1, IRS2, PRKAR1A, SNAP23, and VTI1A, which were identified as the key genes in the comorbidity of PCOS and depression." (PMID 38674428, 2024). "Thus, for the same reason as SNAP23, VTI1A is evidenced to be a key gene in the comorbidity of PCOS and depression." (PMID 38674428, 2024). "Furthermore, the results of the SNP genetic analysis indicated that negative associations were found between rs112568544 at SNAP23 and the patients with PCOS and depression." (PMID 38674428, 2024). "Consequently, it is speculated that PRKAR1A mediates PKA-dependent snapin to work together with SNAP23 in the comorbidity of PCOS and depression." (PMID 38674428, 2024).
Hypertension (1 paper, 2026). The presence of chronic increased pressure in the systemic arterial system. "In the PE rat model, downregulation of GCLM and SNAP23 and upregulation of RHOT2 were significantly correlated with clinical phenotypes such as hypertension and proteinuria, as well as changes in placental inflammatory factor levels (TNF-α, IL-1β, IL-6)." (PMID 41953137, 2026).
ischemia (1 paper, 2013). A hypoperfusion of the BLOOD through an organ or tissue caused by a PATHOLOGIC CONSTRICTION or obstruction of its BLOOD VESSELS, or an absence of BLOOD CIRCULATION. "Despite the fact that synaptosomal-associated protein SNAP-25 has not been detected in astrocytes but SNAP-23, our data revealed mRNA levels coding SNAP-25 were significantly increased in cortical astrocytes 14 days post-ischemia (B3 subpopulation)." (PMID 23940528, 2013).
lung disease (1 paper, 2024). "Direct interactors with the CFTR protein, including SNAP23, KRT19, PPP2R1A, and PPP2R4 proteins, were also identified as lung disease modifiers in a longitudinal study." (PMID 40225935, 2024).
memory impairment (1 paper, 2024). "Moreover, melatonin reverses Aβ1–42‐induced neurotoxicity and memory impairment by increasing the levels of presynaptic proteins (Synaptophysin and SNAP25) and postsynaptic proteins (PSD95 and SNAP23)." (PMID 39500626, 2024).
neuroblastoma (1 paper, 2016). Neuroblastoma (NB) is the most common solid, extracranial childhood tumor. "Immunoblotting revealed that differentiation of SH-SY5Y cells enhanced SNARE cleavage and led to a significant decrease in SNAP23 content confirming that SNARE loss in neuroblastoma cells could be responsible for cell death." (PMID 27121208, 2016). "Our mechanistic insights revealed that loss of ubiquitous SNAP23 due to differentiation coupled to SNAP25 cleavage due to botulinum activity may underlie the apoptotic death of human neuroblastoma cells." (PMID 27121208, 2016).
schizophrenia (1 paper, 2022). A major psychotic disorder characterized by abnormalities in the perception or expression of reality. "SNAP23, SNAP25, SNCA, and GAP43, present in the presynaptic membrane, play essential roles in neurotransmitter release and plasticity and are associated with schizophrenia." (PMID 35062349, 2022).
Skin Cutaneous Melanoma (1 paper, 2022). "The results showed that high expression of SNAP23 was a protective factor in SKCM (Skin Cutaneous Melanoma) and KIRC (Kidney renal clear cell carcinoma)." (PMID 36119081, 2022).
thrombosis (1 paper, 2020). "Our study has fully proved that flow disturbance accelerates the FeCl3-induced thrombosis and the effects are dependent on the VAMP3 and SNAP23-mediated VWF secretion." (PMID 33224946, 2020).
typhoid (1 paper, 2022). "Collectively, these results indicate that the last step in typhoid toxin export is controlled by the VAMP7/SNAP23/STX4 SNARE complex, which targets the typhoid toxin vesicle carrier intermediates for fusion to the plasma membrane and subsequent release of the toxin cargo to the extracellular space." (PMID 35579416, 2022).
tumor (25 papers, 2016 to 2025). "Correlation analysis revealed that high SNAP23 expression was significantly associated with increased tumor damage." (PMID 41274938, 2025). "Further multi-omics analysis revealed that cryoablation activates the lysosomal pathway in tumor tissues, leading to overexpression of key proteins such as SNAP23 (Synaptosome Associated Protein 23) and STXBP2 (Syntaxin Binding Protein 2)." (PMID 38384806, 2024). "In tumor cells, syntaxin-4 and synaptosome-associated protein 23 (SNAP-23) serve as t-SNARE, when vesicle-associated membrane protein-2 (VAMP-2) and VAMP-8 represent v-SNARE." (PMID 31438991, 2019). "The double IF and cross-IP results collectively suggest that PKM2 is associated with SNAP-23 during tumour cell exosome release." (PMID 28067230, 2017). "Next, immunohistochemical (IHC) staining combined with terminal deoxynucleotidyl transferase dUTP nick-end labeling (TUNEL) assay demonstrated that low SNAP23 expression significantly reduced tumor cell damage in specimens from insensitive CRC patients." (PMID 41274938, 2025). "We observed reduced tumor weights and volumes in the SNAP23 knockdown group compared to the control group." (PMID 41274938, 2025). "The in vitro and in vivo models showed that genetic blockade of SNAP23 attenuate the anti-tumor effect of OXA." (PMID 41274938, 2025). "Recent investigations have increasingly focused on the role of SNAP23 in tumorigenesis and tumor progression." (PMID 41274938, 2025). "Given that SNAP23 knockdown significantly enhanced drug sensitivity in vitro, we next assessed the anti-tumor activity in vivo using HT29 cells with stable SNAP23 depletion." (PMID 41274938, 2025). "Cell destruction leads to the activation of anti-tumor immunity due to the release of tumor-related antigens such as SNAP23 and STXBP2, leading to an abscopal effect." (PMID 36612192, 2022). "Notch1 contributes to an immune-suppressive tumor microenvironment by inhibiting the expression of SNAP23 and overexpression of IL-6, IL-8, and CCL5 downstream of the pathway, thus affecting the efficacy of immune-checkpoint inhibitors." (PMID 36119081, 2022). "For example, studies have shown that aerobic glycolysis in tumor cells can promote exosome secretion through the phosphorylation of SNAP23 by its key enzyme PKM2." (PMID 34088337, 2021). "Collectively, these data demonstrate that SNAP23 is essential for let-7a-mediated tumor cell growth." (PMID 33446221, 2021). "Let-7a was enriched in sh-NT CRC cells-derived EVs, but the uptake of EVs by sh-SNAP23 cells promotes tumor growth." (PMID 33446221, 2021). "For example, a study showed that pyruvate kinase type M2 promotes exosome release from tumor cells by phosphorylating SNAP23." (PMID 34088337, 2021). "The localization of SNAP23 (t-SNARE) on the cell membrane has been confirmed to be involved in the secretion of tumor cell derived exosomes." (PMID 34088337, 2021). "Given that let-7a-SNAP23 axis significantly inhibited the tumor growth in vitro, we next using SW480 cells with stable SNAP23 depletion to determine the antitumor activity in vivo." (PMID 33446221, 2021). "Phosphorylated SNAP-23 is the phosphorylated substrate of pyruvate kinase type M2 (PKM2) in tumor cells that can directly promote the release of exosomes." (PMID 31438991, 2019). "Collectively, these studies suggest that PKM2 particularly phosphorylated/dimerized PKM2 can phosphorylate SNAP-23, a key component of exocytosis machinery, to promote tumour cell exosome secretion." (PMID 28067230, 2017). "As shown, tumour cells particularly the cells with high capacity to secrete exosomes, had a significantly higher level of p-SNAP23 compared with myoblast and MEC." (PMID 28067230, 2017). "PKM2, an enzyme whose expression is upregulated in tumour cells whose metabolic needs are met through glycolysis, promotes the release of exosomes from tumour cells by phosphorylating Ser95 of SNAP-23, a component of the synaptosome/SNARE complex." (PMID 28067230, 2017).
tumor (continued). "The results suggest that PKM2-promoted exosome release in tumour cells is through SNAP-23-mediated mechanism." (PMID 28067230, 2017). "The role of SNAP-23 Ser95 phosphorylation in promoting tumour cell exosome secretion was confirmed in cells transfected with the His-tagged SNAP-23 (Ser95→Glu95) construct that mimics constitutively phosphorylated SNAP-23 at Ser95." (PMID 28067230, 2017). "To further examine the role of phosphorylation of SNAP-23 by PKM2 in mediating tumour cell exosome release, we constructed three plasmids expressing SNAP-23 mutants." (PMID 28067230, 2017). "SNAP23 is hyper-expressed in OC tumor tissues compared to normal tissues, and increased expression of SNAP23 is associated with a poor progression free survival (HR = 1.24, 95% CI = 1.07–1.44, p = 0.0042)." (PMID 27855700, 2016). "There is recent evidence that a regulated membrane trafficking pathway mediated by SNAP23 is required for breast cancer cell invadopodium formation and efficient tumor cell invasion in vitro." (PMID 27855700, 2016). "Our findings demonstrate that knockdown of SNAP23 significantly inhibits tumor cell proliferation." (PMID 41274938, 2025). "In addition, significant reduction of SNAP23, VAMP7, and NLRC5 proteins indicates the reduction of cancer-associated protein trafficking, unconventional secretome, and tumor growth." (PMID 37941832, 2023). "Overall, our results demonstrated that let-7a/SNAP23 axis could provide not only effective tumor biomarkers but also novel targets for tumor therapeutic strategies." (PMID 33446221, 2021). "Since much evidence has demonstrated that let-7a functions as a tumor suppressor in various tumors including CRC, we further determined whether SNAP23 is critical for let-7a-regulated tumor growth." (PMID 33446221, 2021). "And the mechanisms of let-7a/SNAP23 pathway in tumor cells need to be more specific." (PMID 33446221, 2021). "Mutation of SNAP-23 Ser95 impairs PKM2-induced tumor cell exosome release, suggesting a non-metabolic role of PKM2 in regulating tumor microenvironments via inducing exosome release." (PMID 33292198, 2020). "Similar to the association pattern seen in TCGA survival data, in vivo tumorigenesis by KRAS-dependent human tumor cells in immune deficient mice required SNAP23 and VAMP3, but not SNAP29." (PMID 31712554, 2019). "We conclude that PKM2, following phosphorylation and dimerization, plays an essential role in not only switching tumour cell metabolism from oxidative phosphorylation to aerobic glycolysis, but also promoting tumour cell exosome secretion via directly phosphorylating SNAP-23." (PMID 28067230, 2017). "Given that SNAP-23 phosphorylation is required for exocytosis and PKM2, particularly phosphorylated PKM2, is associated with SNAP-23 during exosome secretion, we speculated that PKM2 might promote tumour cell exosome secretion through phosphorylating SNAP-23." (PMID 28067230, 2017). "Moreover, the weaken mitochondrial biogenesis revealed in SNAP23 knockdown cells.These findings highlight the multifaceted biological functions of SNAP23 beyond its role in vesicle transport, implicating it in metabolic processes and tumor progression, warranting further investigation." (PMID 41274938, 2025). "Moreover, the analysis of the tumor microenvironment of SKCM in TCGA showed that the expression of SNAP23 was positively correlated with the number of immunes enhancing M1 cells while negatively correlated with the number of immunosuppressive immune Treg cells." (PMID 36119081, 2022). "Finally, a catalytic light chain of botulism toxin E protease engineered to cleave SNAP23 suppresses in vivo tumorigenesis by KRAS-driven tumor cells, indicating that vesicular transporters may provide a therapeutic opportunity in KRAS-dependent malignancies." (PMID 31712554, 2019).
tumor (continued). "The number of SNAP23-positive and TUNEL-positive tumor cells was increased in specimens from sensitive CRC patients, indicating that SNAP23 enhances OXA-induced DNA damage and apoptosis." (PMID 41274938, 2025). "During this period, lysosome-related pathways are activated, resulting in overexpression of SNAP23 and STXBP2, activation of immune effector cells, suppression of the release of immunosuppressive factors, and finally, enhancement of anti-tumor immunity." (PMID 36119081, 2022). "Specifically, we identify SNAP-23, which controls the docking and release of secretory granules or exosome-containing multivesicular bodies, is a substrate of PKM2 in tumour cells." (PMID 28067230, 2017). "Collectively, these results confirm that PKM2 phosphorylation of SNAP-23 at Ser95 is a key to SNARE complex formation and the secretion of exosomes in tumour cells." (PMID 28067230, 2017). "By analyzing the Human Protein Atlas, we compared the protein expression of SNAP23, SNAP25, SNAP29 and SNAP47 in ovarian normal and tumor tissues." (PMID 27855700, 2016). "Furthermore, animal experiments showed that the tumor xenografts of NSG mice injected with EVs increased the tumor size and weight of the SNAP23-depleted SW480 xenografts." (PMID 33446221, 2021). "Importantly, syntaxin‐4, SNAP‐23, and VAMP‐7 were also found to mediate exosome secretion in other types of tumour cell lines, for example, HeLa and A375 cells, suggesting their functional importance and conservation in exosome secretion across diverse tumour types." (PMID 37700095, 2023). "However, the kinase that phosphorylates SNAP-23 in the tumour cell has not been identified." (PMID 28067230, 2017). "To test whether PKM2-promoted tumour cell exocytosis is through SNAP-23-mediated exocytic machinery, we first compared the levels of SNAP-23 and phosphorylated SNAP-23 (p-SNAP-23) in tumour or non-tumour cells." (PMID 28067230, 2017).